MMP9 (matrix metallopeptidase 9)
Diseases named in the same sentence as MMP9 in open-access papers (continued):
Sharing a sentence is not in itself a finding about the gene and the disease.
tumor (continued). "MIF is highly expressed in head-and-neck cancer (HNC) and stimulates functions of neutrophils by enhancing their CXCR2-dependent recruitment and survival and release of CCL4 and MMP9, in turn, promoting tumor progression." (PMID 35842634, 2022). "The 4 markers CD4, CD8, CD68, and MMP9 were compared to the different prognostic markers aimed at detecting any effect of these immune marker expressions on the prognosis of the tumor." (PMID 35083113, 2022). "Both MMP-9 and NOX-2 are associated with basement membrane degradation and, therefore, trigger tumor cell death." (PMID 35681719, 2022). "IHC staining using antibodies for specific detection of Ki67 (proliferation), cleaved caspase-3 (apoptosis) and MMP-9 (invasion) further confirmed the inhibitory effect of tRF3008A on tumor progression." (PMID 35065674, 2022). "It promotes TGF‐β signaling at the tumor–bone interface by proteolytic activation of matrix metallopeptidase 9 (MMP9), thus promoting tumor growth and enhancing osteoclast activation and subsequent bone resorption." (PMID 35067006, 2022). "MMP2 and MMP9 that play a role in tumor invasion and metastasis are proteolytic enzymes involved with extracellular matrix (ECM) degradation." (PMID 35371324, 2022). "Immunohistochemical analysis of the tumour tissues showed changes in the protein expression of MMP9, vimentin, Bax, Bcl‐2, p‐p65, CDK9, MMP2, N‐cadherin and MIF." (PMID 35060345, 2022). "Among MMPs, MMP-2 and MMP-9 have drawn much attention for their implication in tumor invasion and metastasis." (PMID 35887021, 2022). "MMP-2 and MMP-9 are zymogens that are secreted primarily by tumor cells and stromal cells and play an essential role in extracellular matrix degradation, tumor invasion, and metastasis." (PMID 35875198, 2022). "The analysis revealed that the relative expressions of AKT1, MMP2, and MMP9 genes were increased in HCC tumour tissues (n = 373) compared with the normal samples (n = 50)." (PMID 35811356, 2022). "It would be interesting to see the effects of GLV-1H255 relative to GLV-1h68 in a tumor model that differs in ECM composition or response to MMP-9." (PMID 35155581, 2022). "Andecaliximab (ADX) is a monoclonal antibody that inhibits matrix metalloproteinase 9 (MMP9), an extracellular enzyme involved in matrix remodeling, tumor growth, and metastasis." (PMID 35773363, 2022). "At the same time, the regulation of VEGF by MMP-9 can promote tumor angiogenesis, which is beneficial to tumor colonization." (PMID 36080397, 2022). "This study provides a theoretical and scientific basis for the application of GNP in tumor metastasis and MMP-9 expression." (PMID 35954126, 2022). "Zoledronate, a third-generation bisphosphonate, is cytotoxic to TAMs that express matrix metalloproteinase-9 (MMP9) and improves macrophage anti-tumor activity by polarizing monocytes toward pro-inflammatory phenotype." (PMID 36303138, 2022). "These signaling molecules activate MMP-9, a matrix degrading enzyme involved in IL-1β-induced tumor invasion." (PMID 36430487, 2022). "MMP-9 is a gelatinase that mediates the remodeling of the extracellular membrane, and it has been demonstrated to play an important role in tumor angiogenesis by triggering the angiogenic switch." (PMID 35158807, 2022). "Our immunohistochemical analysis of tumor sections also showed a decrease in MMP9 staining in MIR31HG-silenced subcutaneous xenografts." (PMID 35443670, 2022). "MMP-9 degrades basal type IV collagen near tumor cells and then invades other normal tissues, thereby inducing cancer invasion and metastasis." (PMID 36204126, 2022).
tumor (continued). "In SKCM cells, ENO1 overexpression promoted invasion, migration, and proliferation of tumor cells; increased pyruvate and lactate production; and increased β-catenin, MMP-9, MMP-13, and c-Myc levels." (PMID 35925486, 2022). "Increased MMP-9 enzymatic activity reflects invasiveness of a tumor, increased ability to metastasize and increased angiogenesis." (PMID 35325006, 2022). "MMP9_macro expressed genes related to inflammatory chemokines (CXCL2, CXCL3, CXCL8) and genes like MMPs (MMP19, MMP9), which play an important role in tumor tissue remodeling." (PMID 35935940, 2022). "Matrix metalloproteinase 9 (MMP9), a zinc-dependent endopeptidase, plays a central role in the process of tumor cell migration, infiltration, and metastasis." (PMID 35371977, 2022). "From our data, there are some indications that LCN2 can lead to enhanced activation of pro-MMP-9, thereby causing a higher degree of extracellular proteolysis, leading to the tumor-promoting effect of positive co-regulation of MMP-9 and LCN2 by ADAM8." (PMID 35216088, 2022). "This modification can improve the systemic circulating time and significantly enhance cellular uptake post-cleavage by MMP-9 in the tumor microenvironment." (PMID 35845404, 2022). "Despite the role of NGAL and MMP9 in tumor invasion and metastasis has been deeply investigated, the exact involvement of SLC22A17 in cancer development has not been yet clarified." (PMID 36211450, 2022). "Tregs cultured in conditioned medium from OCSCs exhibited increased IL-10 and MMP-9 expression which enhanced the tumor invasion." (PMID 35269636, 2022). "As discussed, immunosuppression in PDAC is not induced by a single cell type or component, but by a combination of cells such as Tregs, MDSCs or CAFs, secreting multiple tumor-promoting mediators such as IL-10 or MMP9." (PMID 35205732, 2022). "Elevated levels of matrix metalloproteinases (MMPs), especially MMP-9, are considered as an important factor in hepatocarcinogenesis, being a promoter of tumor invasion and angiogenesis as well." (PMID 35081125, 2022). "VEGF, sequestered in the tumor extracellular matrix, after being released by MMP-9, increases further neutrophilic expression of MMP-9 in a positive feedback fashion." (PMID 35158807, 2022). "The results demonstrated that the overexpression of BHLHE41 significantly decreased the levels of N-cadherin, vimentin, and MMP9 and significantly increased the level of E-cadherin in tumor tissue (P < 0.01)." (PMID 35615737, 2022). "Analysis of tumor edge (L2 and L3) and core tumor (L4) with strongly proliferating and vascularized zones revealed reversed expression patterns for MMP9, ADAM8, and miR-181a-5p." (PMID 35371977, 2022). "PRL-3 and MMP9 jointly affect tumor metastasis; hence, the combined detection of their expression in CRC can more comprehensively evaluate tumor metastasis potential." (PMID 35574414, 2022). "The activation of TLR2-induced matrix metalloprotease (Mt1-mmp) and Mmp9 expression in MG and resulted in tumor expansion and metastasis." (PMID 36311702, 2022). "Correspondingly, LDH-C4 can be induced by EMT and the expression of MMP-2 and MMP-9 to achieve xenograft tumor growth and metastatic potential by the activation of the PI3K/AKT pathway in vivo." (PMID 36408133, 2022). "Next, an additional band of ~82 kDa, likely corresponding to MMP-9 active form was observable in tumor samples, while it was very faint to undetectable in normal skin specimens." (PMID 36518899, 2022). "MMP-2 and MMP-9 catalyze the degradation of most extracellular matrix and basement membrane components and promote tumor angiogenesis, thereby enhancing tumor invasion and metastasis." (PMID 36276736, 2022). "The HA-dependent CD44 receptor has been shown to proteolytically activate MMP-9 on the cell surface leading to the promotion of tumor invasion and angiogenesis." (PMID 36613567, 2022).
tumor (continued). "Studies have suggested that astrocytes can secrete matrix metalloproteinase (MMP)-2 and MMP-9, remove matrix components on the surface of tumor cells and the surrounding matrix, and promote the invasion and metastasis of tumor cells." (PMID 36338717, 2022). "As a result, the mRNA expression of VEGF and MMP-9 on day 24 was significantly lower in the tumor tissues of the radotinib 100 mg/kg group compared to the control group, radotinib 0 mg/kg group." (PMID 35503759, 2022). "MMP9 expression is generally detected at tumor margins and at the endothelial proliferation sites, which relates its expression with angiogenesis and invasion." (PMID 35053605, 2022). "MMP9 has been identified as a biomarker in various cancers, mainly when tumor expression is considered." (PMID 34980260, 2022). "The tumor volume, expression levels of Ki67, MMP9, and CD206 in the OXA + A-SFE group were less than those in the OXA group." (PMID 36408222, 2022). "Our results demonstrated that 6-gingerol treatment inhibited HIF-1α target genes, including MMP-9, vimentin and snail, which are correlated with tumor metastasis." (PMID 35408505, 2022). "Despite a greater proportion of M1 macrophages in the TME, M2 macrophages expressed higher gene level of CD163, MRC1 (CD206), TGF-β, IL10, VEGFA, and MMP9, which exhibited stronger tumor-promoting ability." (PMID 35033156, 2022). "In this study, neutrophils were identified as an important source of MMP-9, and their functional involvement in tumor angiogenesis was demonstrated by the suppression of tumor angiogenic switch after depletion with the anti-Gr-1 antibody." (PMID 35158807, 2022). "MMP9 levels exhibited differences between non-tumor adjacent tissue and tumor tissue, with tumor tissue MMP9 levels higher than in non-tumor adjacent tissue." (PMID 36139645, 2022). "The selected protumorigenic genes (Lrp5, MMP9, Runx2, TGFβ, and Snail) were downregulated in Oct4 CM-treated 4T1.2 parental cells, while they were elevated in Oct4-overexpressing tumor cells and reduced in Oct4-silenced tumor cells." (PMID 35547745, 2022). "Specifically, we showed that the knockdown of LPAL2 accelerates tumor growth and metastasis, and that MMP9 is directly regulated by LPAL2." (PMID 36010685, 2022). "Our results provide solid evidence that AITC can significantly reduce VEGF and MMP-9 in the tumor samples of GBM8401/luc2 cell xenograft mice." (PMID 36142326, 2022). "The matrix metalloproteinases (MMPs) including MMP-2 and MMP-9 belong to a family of proteinases that can catalyze the cleavage of extracellular matrix components, thus favoring tumor cell migration, invasion, and metastasis." (PMID 36177059, 2022). "Immunohistochemical results of the tumor tissue show that the expression levels of Ki67 and MMP9 as well as EGFR were significantly reduced in CA-treated groups compared with the CA-untreated group." (PMID 35645793, 2022). "MMP-9 promotes tumor angiogenesis by activating VEGF and VEGF receptor interactions in endothelial cells." (PMID 36060811, 2022). "In the vascular endothelium, this pathway is activated after VEGFR2 binding; this increases MMP-9 secretion and enhances the invasion ability of tumor cells." (PMID 36338717, 2022). "They will help further evaluate the effects of GsRb1 in the progression of cardiac remodeling and tumor metastasis via MMP-9 inhibition, as well as confirm the efficacy and safety of the compound." (PMID 36432152, 2022). "Previous studies provided evidence that MMP2 and MMP9 triggered cell migration and invasion, and they were two major MMPs involved in tumor angiogenesis, increasing the bioavailability of VEGF." (PMID 35494062, 2022). "Tumor development was monitored every three days while anti- PD1/PD-L1 therapies were given every three days and HMOX1/MMP9/TNFRSF11B antibody treatments were given every day until tumor capture on the ninth day." (PMID 36189226, 2022).
tumor (continued). "Lack of CD44 appears to completely hinder the ability of primary microglia to upregulate MMP9 in response to tumor cells." (PMID 35992852, 2022). "We investigated the expression of N-cadherin, E-cadherin, vimentin, and MMP9, and found that the epithelial characteristics of tumor cells in the 3D bioprinted environment were decreased, whereas the mesenchymal characteristics increased." (PMID 35983036, 2022). "In conclusion, circulating MMP9 is predictive of bevacizumab efficacy and is released by tumor-infiltrating neutrophils." (PMID 34980260, 2022). "In this review, we present the current state of knowledge on MMP9 and its role in cancer growth in the context of cell adhesion/migration, cancer-related inflammation, and tumor microenvironment formation." (PMID 35406619, 2022). "MDSCs are capable of secreting MMP9 for promoting the anti-PD1 resistance cleavage of PD-L1 surface expression, which is dependent of MMP9, and hypoxia restricts the anti-tumor function exhibited by anti-PD1 Abs." (PMID 36375474, 2022). "HSP72 and HSP105 in sEVs in the sera of melanoma, lung cancer and BC patients activate dendritic cells and trigger IL-6 production, which promote tumor invasion by increasing MMP9 expression." (PMID 36499561, 2022). "Aminobisphosphonates reduce MMP9 expression and the number of macrophages in the tumor stroma and decrease MDSCs infiltration in bone marrow and peripheral blood by decreasing serum pro-MMP9 and VEGF." (PMID 36237333, 2022). "Betulinic acid significantly reduced Ki67-positive and MMP-9-positive cells in the tumor tissues of mice inoculated with 786-O cancer cells." (PMID 36615262, 2022). "As one of the MMPs, MMP-9 is a paracrine regulator of tumor progression that degrades ECM, destructs the basement membrane, and spreads cancer through the circulatory system." (PMID 36311793, 2022). "The presence of tumor cells was positively correlated with pleural levels of MMP-9 but negatively correlated with pleural levels of lactoferrin." (PMID 35626131, 2022). "Related research findings found that downregulation of FOXP3 inhibited tumor cell invasion by reducing MMP-9 and MMP-2." (PMID 36185217, 2022). "It has been demonstrated that in vivo transfection of IFN-β-expressing vector downregulated MMP-9 and Bv8 expression in neutrophils isolated from the bone marrow of tumor-bearing mice." (PMID 35158807, 2022). "TANs also play a role in tumor invasion and angiogenesis in primary and metastatic sites by generating MMP9, VEGF, HGF, PAF, IL-10." (PMID 36419156, 2022). "Numerous studies have found that MMP9 plays an essential role in invasion and metastasis of tumor, affecting tumor microenvironmental factors, with great value as a biomarker of various specific cancers." (PMID 35321506, 2022). "At the same time, MMP-9 can degrade type IV collagen of basement membrane, destroy the integrity of basement membrane, and also contribute to the invasion and metastasis of tumor cells." (PMID 36246294, 2022). "MMP9 is a matricellular protein causing extracellular matrix (ECM) remodelling, so it can stimulate tumour progression, and influence the function of and cell adhesion molecules." (PMID 35874525, 2022). "On the other hand, neutrophils promote the establishment of tumor cells in the lung via the induction of MMP-9-mediated angiogenesis." (PMID 36294305, 2022). "And MMP-9 also effectively reduces the tumor killing-effect of T cells via cutting the MHC class I molecule, cell surface antigen-presenting complex molecules expressed in melanoma cells." (PMID 36776395, 2022). "The relative expressions of AKT1, MMP2, and MMP9 genes were higher in tumour tissues than in non‐neoplastic liver tissues." (PMID 35811356, 2022).
tumor (continued). "The results indicated that G6PD changed cell cycle dynamics, facilitated cell proliferation, promoted migration in vitro, and enhanced ccRCC tumor growth in vivo, probably by upregulating Cyclin E1 and MMP9." (PMID 34975298, 2022). "This study also suggested that FOXP3 can upregulate the expression of MMP2 and MMP9, both of which play a promoting role in tumor metastasis." (PMID 36235242, 2022). "MMP9 (Matrix Metallopeptidase 9) is a member of metalloproteinases (MMPs) that plays an important role not only in tumor invasion and migration, but also in inflammation and remodeling in UC." (PMID 35719390, 2022). "Two mutated, amplified, and over-expressed tumor antigens, IGF2BP2 and MMP9, were found to be associated with clinical outcomes and the abundance of antigen-presenting cells (APCs)." (PMID 36569935, 2022). "Invasion is an important feature of malignant tumors, and MMP2 and MMP9 are the most widely studied matrix metalloproteinases that play important roles in tumor cell invasion and metastasis." (PMID 35898928, 2022). "We found that the anti‐Chi3L1 antibody inhibited MMP9 and cyclin D1 expression compared with the vehicle‐treated tumor tissues." (PMID 34861103, 2022). "MDSCs are recruited and activated by IL33, and produce VEGF, FGF, and MMP9 for inducing angiogenesis and tumor invasion in collaboration with other ST2+ cells, including Mø and mast cells." (PMID 36211375, 2022). "PKC isoforms are important for tumor promotion and activation of the MMP-9-related signaling pathway." (PMID 35840633, 2022). "Due to its role in many processes related to tumor progression, MMP9 seems to be an attractive target for anticancer therapies." (PMID 35406619, 2022). "Currently, MMPs are recognized as the most important enzymes for ECM degradation, and in particular, the abnormal expression of MMP-2 and MMP-9 can lead to accelerated tumor progression." (PMID 36432106, 2022). "The expression levels of G6PD, Cyclin E1 and MMP9 protein were significantly increased in ACHN-G6PDOE-derived tumor tissues, whereas they were obviously decreased in Caki-1-G6PDSi-derived tumor tissues compared with the corresponding controls." (PMID 34975298, 2022). "The current study is aimed at testing CD4, CD8, CD68, and MMP9 immunohistochemistry of DLBCL activities with the prognosis of the tumor." (PMID 35083113, 2022). "M2 phenotypic markers, such as CCL22, HIF-1a, Ym1, and MMP-9, which are involved in immunosuppression, angiogenesis, epithelial–mesenchymal transition, and invasion, were significantly upregulated by tumor challenge compared to the WT group." (PMID 35216272, 2022). "As mentioned in our results, immunohistochemical results showed that CA significantly reduced the expression levels of MMP9 and Ki67 in tumor tissues." (PMID 35645793, 2022). "TANs accelerate local tumor invasion by secreting MMP9 and NE to modify and degrade the extracellular matrix (ECM)." (PMID 36230676, 2022). "Two members of secreted matrix metalloproteinases (MMPs), i.e., MMP2 (gelatinase A) and MMP9 (gelatinase B) localize at the surface of tumour cells, and can be encompassed in the group of ectoenzymes." (PMID 35158891, 2022). "This analysis allowed us to identify the median levels of LCN2, SLC22A17, and MMP9 genes and isoforms of each tumor type that were upper to 3rd or lower to 1st quartiles of corresponding normal tissue." (PMID 36211450, 2022). "CXCL7 induces tumor angiogenesis and invasiveness through upregulation of matrix metalloproteinase 9 (MMP9) and endothelial and thylakoid markers." (PMID 35837284, 2022). "In this study, we aim to evaluate the expression of types I (Col1) and IV (Col4) collagens, alpha-smooth muscle actin (a-SMA), and matrix metallopeptidase 9 (MMP-9) in the tumor stroma of small papillary thyroid carcinoma (PTC)." (PMID 36242015, 2022). "Tumor oxygenation increases the production in the tumor epithelium of MMP-9- and NOX-2-derived ROS by PMNs compared with hypoxia." (PMID 35681719, 2022).